PAX8 (paired box 8)
Diseases named in the same sentence as PAX8 in open-access papers (continued):
Sharing a sentence is not in itself a finding about the gene and the disease.
gastric cancer (6 papers, 2018 to 2024). A primary or metastatic malignant neoplasm involving the stomach. "Ectopic expression of miR-612 recapitulated the effect of PAX8 overexpression on gastric cancer cells, causing an inhibition of migration, invasion, EMT, and angiogenesis." (PMID 30021604, 2018). "Our data suggest that increased lymphangiogenesis and somatic mutations of NBN and/or PAX8 could facilitate lymph node metastasis from an intramucosal gastric carcinoma." (PMID 29535844, 2018). "PAX8 exerts a tumor-suppressive effect against gastric cancer cells, largely through induction of miR-612 and repression of FOXM1." (PMID 30021604, 2018). "Our findings reveal the downregulation of PAX8 in gastric cancer cell lines relative to normal gastric epithelial cells, which is in line with a previous study showing decreased expression of PAX8 in gastric adenocarcinomas." (PMID 30021604, 2018). "Knockdown of FOXM1 suppresses the EMT and expression of VEGF in gastric cancer cells, which resembles the phenotype observed in PAX8-overexpressing gastric cancer cells." (PMID 30021604, 2018). "In the present work, we investigated the effects of PAX8 overexpression and knockdown on the aggressive phenotype of gastric cancer cells." (PMID 30021604, 2018). "Functionally, knockdown of miR-612 reversed the tumor-suppressive activity of PAX8, which recapitulates the effect of FOXM1 overexpression on PAX8-overexpressing gastric cancer cells." (PMID 30021604, 2018). "The results showed that overexpression of FOXM1 significantly rescued gastric cancer cells from PAX8-mediated inhibition of cell migration and invasion." (PMID 30021604, 2018). "Collectively, these results support the conclusion that PAX8 acts as a tumor suppressor in gastric cancer." (PMID 30021604, 2018). "In vivo studies revealed that PAX8 overexpression restrained the metastatic activity of gastric cancer cells in nude mice, which was accompanied by compromised angiogenesis." (PMID 30021604, 2018). "In the present study, we explored the biological role of PAX8 in the growth and metastasis of gastric cancer." (PMID 30021604, 2018). "We further checked the involvement of forkhead box M1 (FOXM1), a ubiquitously expressed oncogene that can facilitate gastric cancer progression, in the action of PAX8." (PMID 30021604, 2018). "VEGF expression and secretion was suppressed by PAX8, which provides an explanation for the reduced angiogenic activity in gastric cancer cells." (PMID 30021604, 2018). "Compared to GES-1 gastric epithelial cells, the expression level of PAX8 was significantly reduced in multiple gastric cancer cell lines including AGS, SGC-7901, MKN-28, and MKN-45." (PMID 30021604, 2018). "Our data showed that the expression of FOXM1 was significantly reduced in PAX8-overexpressing gastric cancer cells, but FOXC2, FOXF1, and FOXL1 remained unchanged." (PMID 30021604, 2018). "We found that PAX8-overexpressing gastric cancer cells displayed an upregulation of E-cadherin and downregulation of vimentin." (PMID 30021604, 2018). "By inducting the expression of miR-612, PAX8 is able to downregulate FOXM1 in gastric cancer cells, consequently leading to reduced cancer cell’s invasive, angiogenic, and metastatic potential." (PMID 30021604, 2018). "Our findings suggest that overexpression of PAX8 and/or miR-612 may represent a promising therapeutic strategy for gastric cancer." (PMID 30021604, 2018). "Conversely, knockdown of PAX8 enhanced gastric cancer cell migration and invasion." (PMID 30021604, 2018). "Furthermore, enforced expression of FOXM1 reversed the anti-invasive activity of PAX8 in gastric cancer cells." (PMID 30021604, 2018). "This miR was selectively stimulated by PAX8 overexpression in gastric cancer cells." (PMID 30021604, 2018). "Moreover, knockdown of miR-612 or overexpression of FOXM1 restored the angiogenic activity of gastric cancer cells with stable expression of PAX8." (PMID 30021604, 2018).
gastric cancer (continued). "Since the mRNA and protein levels of PAX8 consistently decreased in gastric cancer cells, this downregulation may occur at the transcriptional level." (PMID 30021604, 2018). "Depletion of PAX8 facilitated the migration and invasion of gastric cancer cells." (PMID 30021604, 2018). "In addition, ectopic expression of PAX8 interfered with the pro-angiogenic activity of gastric cancer cells, as determined by in vitro endothelial cell tube formation assay." (PMID 30021604, 2018). "Overexpression of PAX8 caused a significant suppression of gastric cancer cell migration and invasion, but had no significant impact on cell proliferation." (PMID 30021604, 2018). "Paired box 8 (PAX8) has been documented to be downregulated in gastric cancer." (PMID 30021604, 2018). "Therefore, we provide evidence that PAX8-mediated reduction of FOXM1 in gastric cancer cells is ascribed to induction of miR-612." (PMID 30021604, 2018). "Therefore, restoration of PAX8 expression may offer therapeutic benefits in the treatment of gastric cancer." (PMID 30021604, 2018). "The mechanism for PAX8 downregulation in gastric cancer is currently unknown." (PMID 30021604, 2018). "PAX8 overexpression inhibited epithelial-mesenchymal transition (EMT) and pro-angiogenic activity of gastric cancer cells." (PMID 30021604, 2018). "PAX8 silencing led to an increase in VEGF production and enhanced the angiogenic activity of gastric cancer cells." (PMID 30021604, 2018). "The differential expression of Paired Box Protein 8 (PAX8) and Carbohydrate Antigen 125 (CA125) aids in distinguishing MOC, with 35% and 24% of primary MOCs expressing these markers, respectively, a contrast to their absence in early gastric cancer." (PMID 39040449, 2024). "To confirm the expression of PAX8 in gastric cancer, we examined the mRNA and protein expression of PAX8 in 19 pairs of gastric cancer and adjacent noncancerous gastric tissues." (PMID 30021604, 2018). "Next, we examined the effect of PAX8 overexpression on EMT and angiogenic of gastric cancer cells." (PMID 30021604, 2018). "Quantitative real-time PCR assay revealed that PAX8 mRNA levels were significantly lower in gastric cancer than those in adjacent noncancerous tissues (P = 0.0016)." (PMID 30021604, 2018). "It has been reported that PAX8 expression is weak or absent in gastric cancer." (PMID 30021604, 2018). "Our work identifies PAX8 as a key negative component of the metastatic cascade in gastric cancer." (PMID 30021604, 2018).
glioma (6 papers, 2011 to 2025). A benign or malignant brain and spinal cord tumor that arises from glial cells (astrocytes, oligodendrocytes, ependymal cells). "In earlier studies, we demonstrated that increased PAX8 expression in glioma cell lines was associated with the expression of telomerase." (PMID 24602166, 2014). "The silencing PAX8 in several glioma cell lines caused a marked reduction in cell number, which is partly explained by an increase in apoptosis." (PMID 24602166, 2014). "The PAX8-knockdown led to a reduction in cell number in all the glioma cell lines (P < 0.01, PAX8 siRNA-knockdown compared with all controls)." (PMID 24602166, 2014). "Our data showed that PAX8 is increased in most high-grade gliomas and is a pro-survival factor for glioma cells." (PMID 24602166, 2014). "Here, we surveyed the PAX8 expression in a range of brain tumours, including different grades of gliomas and varieties of telomere maintenance mechanisms." (PMID 24602166, 2014). "BCL2 silencing resulted in a reduction in glioma cell growth similar to the reduction observed with PAX8 silencing at 48–96 hours post-transfection (P < 0.01, BCL2 siRNA compared with controls)." (PMID 24602166, 2014). "Stimulation of TA, hTERT and hTR had been found by the oncofetal protein Pax8 in human glioma." (PMID 27322326, 2016). "The current study represents the first extensive analysis of the PAX8 expression levels in gliomas." (PMID 24602166, 2014). "The silencing of PAX8 by siRNA was performed in three glioma cell lines (A172, SF295, and U118MG) to examine whether reduced PAX8 expression led to a reduction in glioma cell growth." (PMID 24602166, 2014). "Increased PAX8 expression was frequently detected in high-grade gliomas." (PMID 24602166, 2014). "In gliomas, the chromosome 2q13 locus, where the PAX8 gene is located, is not a glioma susceptibility locus (OMIM #137800), but other mechanisms for the increased PAX expression in cancer have been described." (PMID 24602166, 2014). "In low-grade gliomas, PAX8-positive cases were infrequently observed." (PMID 24602166, 2014). "Additionally, co-activators of PAX8 are increased in gliomas." (PMID 24602166, 2014). "Our results are also consistent with another study in which the transcriptional target of PAX8, WT1, was decreased in low-grade compared with high-grade gliomas." (PMID 24602166, 2014). "Reduced PAX8 expression produced a reduction in the BCL2 expression levels, and BCL2 inhibition by siRNA-knockdown reduced the glioma cell growth rate." (PMID 24602166, 2014). "Similarly, miR-34a regulates PDGFRA and PAX8, two genes which are known to be involved in childhood CNS tumors, as especially PDGFRA has been studied for its role in gliomas." (PMID 34771655, 2021). "Because PAX8 binds to the promoter region of BCL2 and WT1 and enhances transcription, we investigated whether the downregulation of PAX8 would decrease the BCL2 and WT1 expression levels in glioma cells." (PMID 24602166, 2014). "The prevalence of increased PAX8 expression has not been extensively explored in glioma, especially with regard to the effect of increased PAX8 expression in telomerase-negative gliomas." (PMID 24602166, 2014). "The predominance of high-grade gliomas expressing high levels of PAX8 and the virtual absence of PAX8 expression in normal brain makes PAX8 signalling an appealing therapeutic target pathway." (PMID 24602166, 2014). "Because PAX8 is absent in normal brain tissue, it may be a promising therapeutic target pathway for treating aggressive gliomas." (PMID 24602166, 2014). "PAX8 expression was measured in 156 gliomas including telomerase-negative tumours, those with the alternative lengthening of telomeres (ALT) mechanism or with a non-defined telomere maintenance mechanism (NDTMM), using immunohistochemistry and quantitative PCR." (PMID 24602166, 2014). "The majority of the low-grade gliomas and normal brain cells were PAX8-negative." (PMID 24602166, 2014).
insomnia (6 papers, 2019 to 2025). A sleep disorder characterized by difficulty in falling asleep and/or remaining asleep. "Considering that we also observed phenotypic correlations between sleep duration, insomnia and graph theory measures, it is possible that variants in or near PAX8 and other genes in this region may play a role in the regulation of genes associated with functional brain network properties and sleep." (PMID 34272439, 2021). "The effect of Mongolian medical warm acupuncture (MMWA) on insomnia is related to the regulation of miR-101a and PAX8." (PMID 37614343, 2023). "Furthermore, clinical insomnia associations highlighted two loci that were primarily associated with RLS, MEIS1 consistent with earlier studies, and PRMT6, as well as five additional shared loci and one locus specific to clinical insomnia, PAX8 (PP = 0.8)." (PMID 41332830, 2025).
lymphoma (6 papers, 2016 to 2024). A malignant (clonal) proliferation of B- lymphocytes or T- lymphocytes which involves the lymph nodes, bone marrow and/or extranodal sites. "This case report demonstrates a pitfall for PAX8 immunoreactivity and acts as a reminder that lymphoma should be included in the differential diagnosis of a PAX8 positive, epithelial cell marker negative tumor of unknown primary origin." (PMID 28634564, 2017). "Histologically, we never observed sarcomas or lymphomas arising in electroporated animals and, accordingly, all tumors analyzed expressed molecular hallmarks of human HGSOC, including Cytokeratin-7 (CK7), Wilms Tumor 1 (WT1), Cancer Antigen 125 (CA-125), Paired box 8 (Pax-8), and high Ki67." (PMID 35082152, 2022).
PEComas (6 papers, 2016 to 2025). "Among TFE3-rearranged tumors arising in the kidney, most have been viewed as morphologically heterogeneous carcinomas staining for the tubular marker PAX8, whereas some others as mesenchymal neoplasms named PEComas." (PMID 39410016, 2024). "Lack of immunoreactivity for HMB45, melan-A, desmin, pan-CK, PAX8, and S100 excluded the possibility of perivascular epithelioid cell tumor, clear cell sarcoma, metastatic renal cell carcinoma, granular cell tumor, and paraganglioma." (PMID 35626258, 2022). "The immunohistochemical analysis of renal TFE3-rearranged PEComas consistently shows a robust expression of cathepsin K (99%) and melanogenesis markers (HMB45 91% and MART1/MELAN A 80%) along with negativity for PAX8, cytokeratins, and S100." (PMID 39410016, 2024). "However, this also raises the differential of epithelioid PEComas, sharing the same immunoexpression pattern, except being PAX8 negative and CD68 positive." (PMID 34680535, 2021). "These tumors can be excluded by immunohistochemistry, as PEComas and melanotic Xp11.2 translocation cancer are negative for renal cell markers (CD10, PAX2 and PAX8) and positive for MelanA and HMB45." (PMID 27733182, 2016).
prostatic adenocarcinoma (6 papers, 2023 to 2025). "This was based on the expression of a cell lineage restricted transcription factor PAX8 in both lesions and absence of its expression in either normal urothelium or other urological malignancy including prostatic adenocarcinoma." (PMID 40182577, 2025). "Immunohistochemistry was negative for CK20, CK5/6, PAX-8, TTF-1, PSA, and PIN4, but positive for PSAP and NKX3.1, consistent with mucin-producing prostate adenocarcinoma." (PMID 41293260, 2025). "Immunohistochemical analysis revealed these atypical cells did not express general thyroid markers (PAX8 and TTF1), but rather expressed the prostate markers NKX3.1 and PSA, confirming the presence of prostate adenocarcinoma which had metastasized to the known thyroid gland nodule." (PMID 38879699, 2024).
thymic carcinoma (6 papers, 2018 to 2025). Thymic carcinoma (TC) is a type of thymic epithelial neoplasm characterized by a high malignant potential. "In mediastinal mass biopsies, PAX8 could be useful to discriminate the origin of cancer cells, because its specificity in distinguishing thymic carcinoma from carcinomas originating from the lung." (PMID 40506992, 2025). "When distinguishing thymic carcinomas from lung primary squamous carcinomas, determining PAX8, CD5, and CD117 positivity in thymic carcinomas can be useful to distinguish thymic carcinomas from metastatic carcinomas." (PMID 37510144, 2023). "Immunohistochemical staining for PAX8, CD5, c-KIT, TdT, and CD1a also demonstrated features that are characteristic to thymic carcinoma." (PMID 34328560, 2021). "On the other hand, several reports have described immunohistochemical examination of thymic carcinoma showing positive results for CD5, c-kit, or PAX8." (PMID 30446840, 2018). "However, immunohistochemical evaluation, including expression patterns of PAX8, CD5, c-KIT, TdT, and CD1a that are characteristic to thymic carcinoma, confirmed the diagnosis in our patient." (PMID 34328560, 2021).
acute kidney injury (5 papers, 2018 to 2024). Sudden and sustained deterioration of the kidney function characterized by decreased glomerular filtration rate, increased serum creatinine or oliguria. "Where there is a link between PAX8 expression in acute kidney injury and greater risk of transitioning to chronic kidney damage is a question that awaits some future studies." (PMID 36140438, 2022). "We also showed that myoglobin provoked acute kidney injury followed with large extent of renal damage, was associated with strong nuclear expression of PAX8 in proximal tubular cells." (PMID 36140438, 2022). "For example, PAX2 and PAX8 have been shown to be re-expressed in postnatal kidneys in response to acute kidney injury, nephrotoxicity, and regenerative changes." (PMID 37511191, 2023). "Suppression of Itgb1 in Pax8 expressing cells impairs glomerular and tubular function leading to progressive renal failure." (PMID 30271355, 2018). "PAX8 has been reported to show enrichment with pathways that regulate apoptosis and RNA polymerase II transcription, and the PAX8 protein is believed to play a role in regeneration and recovery following acute kidney injury." (PMID 38787831, 2024). "Pax8 is notably a nephric-lineage transcription factor required for renal organogenesis potentially involved in regeneration and recovery after acute renal injury and Sox activation is an early transcriptional response to acute kidney injury." (PMID 37124606, 2023). "On the contrary, biopsy samples of the patients with acute kidney injury with unknown etiology showed only a few proximal tubular epithelial cells marked as weakly PAX8 positive." (PMID 36140438, 2022). "Considering these findings, we can assume that PAX8 protein might be involved in regeneration process and recovery after acute kidney injury." (PMID 36140438, 2022). "However, we reported strong nuclear PAX8 expression in proximal tubular cells in acute kidney injury provoked by myoglobin casts tubular obstruction." (PMID 36140438, 2022). "In order to investigate expression of PAX8 transcription factor in acute kidney injury (AKI) and chronic kidney diseases (CKD), immunohistochemical analysis was performed." (PMID 36140438, 2022). "Moreover, all 25 autopsy cases of acute kidney injury were devoid of PAX8 staining, even considering kidney structures such as collecting ducts and distal tubuli that were always positive in all examined biopsy samples and consequently used as internal positive control for PAX8 immunostaining." (PMID 36140438, 2022).
cervical adenocarcinoma (5 papers, 2014 to 2025). An adenocarcinoma arising from the cervical epithelium. "Expression of PAX8 in the setting of invasive cervical adenocarcinomas is less well studied, with only a few reported as positive." (PMID 33504059, 2021). "According to the largest study focusing on this topic, gastric type cervical adenocarcinomas are positive for CK7 in 100% of cases, CK20 in 49%, CDX2 in 51%, Ca125 in 80%, PAX8 in 68%, ER in 6%, PR in 9% and MUC6 in 81% of cases." (PMID 33706757, 2021).
clear cell ovarian cancer (5 papers, 2015 to 2025).
diabetes (5 papers, 2019 to 2025). "We recently reported that loss-of-function mutations in the human PAX8 gene are associated with gestational diabetes mellitus and potentially with type 2 diabetes mellitus in males." (PMID 31518338, 2019). "Additionally, pioglitazone—a PPARγ agonist approved for diabetes—has demonstrated the ability to reduce tumor size and prevent metastasis in animal models of PAX8/PPARγ fusion-positive FTC, with preliminary clinical evidence supporting its use [NCT01655719]." (PMID 41590496, 2025).
mesothelioma (5 papers, 2013 to 2025). A usually malignant and aggressive neoplasm of the mesothelium which is often associated with exposure to asbestos. "The nuclei of clear cell tumor of the ovary diffusely express PAX-8, so PAX-8 is often used in the differential diagnosis of mesothelioma." (PMID 39605894, 2024). "The immunohistochemical expression of Pax-8, BrafV600E, and Ber-EP4 can be differentiated from mesothelioma." (PMID 40502629, 2025). "The patient also showed strong positive PAX-8 staining; for this reason, some pathological experts did not agree with the diagnosis of mesothelioma." (PMID 39605894, 2024).